PPM1E (protein phosphatase, Mg2+/Mn2+ dependent 1E)
Description:
Protein phosphatase that inactivates multifunctional CaM kinases such as CAMK4 and CAMK2 (By similarity). Dephosphorylates and inactivates PAK. May play a role in the inhibition of actin fiber stress breakdown and in morphological changes driven by TNK2/CDC42. Dephosphorylates PRKAA2 (By similarity).
Synonyms: CaMKP-N; CaMKN; KIAA1072; POPX1; PP2CH; CAMKPN
Tractability: PROTAC: ubiquitination databases record sites on it; its protein half-life has been measured.
Gene: Protein-coding gene on chromosome 17 (58,755,854 to 58,985,179, forward strand). Ensembl gene ENSG00000175175.
Subcellular location: Nucleus; Cytoplasm
Subcellular location (Human Protein Atlas): Nucleoli; Nucleoplasm
Pathways (Reactome):
Neuronal System: Negative regulation of NMDA receptor-mediated neuronal transmission
Gene Ontology:
Molecular function: protein binding; protein serine/threonine phosphatase activity; cation binding
Biological process: cellular response to lipopolysaccharide; cellular response to xenobiotic stimulus; negative regulation of protein kinase activity; peptidyl-threonine dephosphorylation; positive regulation of stress fiber assembly
Cellular component: cytoplasm; nucleus; protein-containing complex
Genetic constraint (gnomAD): Loss-of-function variants: 21 observed, 63.23 expected, observed/expected ratio (o/e) 0.33, 90% interval 0.23 to 0.48. The upper end of that interval is the gene's LOEUF score, 0.48, which puts it in group 2 of 6, group 1 being the genes least tolerant of losing a copy. Missense variants: 712 observed, 952.85 expected, observed/expected ratio (o/e) 0.75, 90% interval 0.7 to 0.8. Synonymous variants: 352 observed, 370.9 expected, observed/expected ratio (o/e) 0.95, 90% interval 0.87 to 1.04.
Homologues: Orthologues: chimpanzee PPM1E (99% identical), macaque PPM1E (99% identical), dog PPM1E (93% identical), pig PPM1E (92% identical), mouse Ppm1e (90% identical), rat Ppm1e (89% identical), guinea pig PPM1E (88% identical), rabbit PPM1E (76% identical), tropical clawed frog ppm1e (59% identical), zebrafish ppm1e (46% identical), Drosophila melanogaster CG10376 (17% identical), Caenorhabditis elegans pdp-1 (11% identical), and 1 more. Paralogues in human: PPM1F (28% identical), PPM1D (16% identical), PPM1B (15% identical), PPM1N (14% identical), ILKAP (14% identical), PPM1G (14% identical), PPM1A (13% identical), PPM1K (13% identical), PPM1J (13% identical), PPM1L (12% identical), PPM1H (12% identical), PPM1M (12% identical), and 4 more.
Diseases named in the same sentence as PPM1E in open-access papers:
PPM1E is named in the same sentence as 12 diseases in open-access papers, as found by Europe PMC text mining. Sharing a sentence is not in itself a finding about the gene and the disease. The quoted sentences say what the papers report.
breast carcinoma (2 papers, 2020 to 2022). "According to such additional filter, six cancer-specific proteins in colon cancer (CEACAM8, CDH17, GLOD5, PPM1E, TRIM16, EPCAM) and one in breast cancer (CCR9) were identified." (PMID 36243758, 2022). "According to such parameters, six cancer-specific proteins in colon cancer (CEACAM8, CDH17, GLOD5, PPM1E, TRIM16, EPCAM), one in breast cancer (CCR9) and none in prostate cancer were identified." (PMID 36243758, 2022).
gastric cancer (2 papers, 2017 to 2022). A primary or metastatic malignant neoplasm involving the stomach. "Next, we focused on the possible cause of Ppm1E upregulation in gastric cancer tissues and cells." (PMID 28423719, 2017). "Therefore, miR-135b-5p depletion could be the cause of Ppm1E upregulation in human gastric cancer tissues/cells." (PMID 28423719, 2017). "In gastric cancer (GC), the CircHAS2/miR-944/PPM1E axis promotes the proliferation, invasion, and migration of GC cells." (PMID 36077769, 2022). "To further confirm the function of Ppm1E in gastric cancer cell behaviors, we constructed the Ppm1E-expressing vector." (PMID 28423719, 2017). "Here, we showed that Ppm1E was significantly upregulated in both human gastric cancer tissues and gastric cancer cell lines, which was correlated with AMPKα dephosphorylation/inhibition." (PMID 28423719, 2017). "In summary, we show that Ppm1E is upregulated in both human gastric cancer tissues/cell lines, which apparently is important for shutting down AMPK signaling and promoting cancer cell proliferation." (PMID 28423719, 2017). "Reversely, forced over-expression of Ppm1E induced further AMPK inhibition to promote gastric cancer cell proliferation." (PMID 28423719, 2017). "In the current study, we tested expression and potential function of Ca2+/calmodulin-dependent protein kinase phosphatase (Ppm1E), an AMPKα phosphatase, in human gastric cancers." (PMID 28423719, 2017). "In this study, we show that Ppm1E, the AMPKα phosphatase, is significantly upregulated in human gastric cancer tissues and cell lines, which is possibly important for shutting down AMPK, thus promoting cancer cell proliferation." (PMID 28423719, 2017). "First, we tested Ppm1E expression in human gastric cancer tissues, and compared with the surrounding normal gastric tissues." (PMID 28423719, 2017). "Together, Ppm1E upregulation in human gastric cancer is important for cell proliferation, possible via regulating AMPK-mTOR signaling." (PMID 28423719, 2017). "In this study, we showed that Ppm1E knockdown by shRNA activated AMPK in gastric cancer cells, which led to mTORC1 in-activation and proliferation inhibition." (PMID 28423719, 2017). "Following studies will be needed to confirm that mTORC1 inhibition is the reason of gastric cancer cell proliferation inhibition by Ppm1E shRNA." (PMID 28423719, 2017). "Remarkably, microRNA-135b-5p (“miR-135b-5p”), an anti-Ppm1E microRNA, was downregulated in both human gastric cancer tissues and cells." (PMID 28423719, 2017). "Therefore, Ppm1E, the AMPKα phosphatase, has the potential to be a novel and valuable oncotarget protein for human gastric cancer." (PMID 28423719, 2017). "Therefore, Ppm1E over-expression facilitates mTORC1 activation and promotes gastric cancer cell survival and proliferation." (PMID 28423719, 2017). "We also tested Ppm1E expression in human gastric cancer cell lines." (PMID 28423719, 2017). "Ppm1E upregulation, AMPK inhibition and mTORC1 activation were also observed in human gastric cancer cell lines (AGS, HGC-27, and SNU601)." (PMID 28423719, 2017). "Ppm1E knockdown by shRNA then activated AMPK and significantly inhibited human gastric cancer proliferation." (PMID 28423719, 2017).
schizophrenia (2 papers, 2013 to 2020). A major psychotic disorder characterized by abnormalities in the perception or expression of reality. "Very recently, genome-wide association studies suggested that single nucleotide polymorphisms found in the loci for CaMKP-N (PPM1E) and for CaMKP (PPM1F) are associated with testicular germ cell tumor and with both schizophrenia and bipolar disorders, respectively." (PMID 23991411, 2013).
thyroid cancer (2 papers, 2022 to 2024). "Pearson correlation analysis showed that PPM1E and miR-135a-5p are negatively correlated in thyroid cancer with correlation coefficient of –0.327." (PMID 35368894, 2022). "The results of this study showed that miR-135a-5p was underexpressed in thyroid cancer cells, and the overexpression of miR-135a-5p inhibited the expression of PPM1E protein." (PMID 35368894, 2022). "The expression levels of LINC01087, miR-135a-5p, and PPM1E in thyroid carcinoma tissues were detected by QRT-PCR." (PMID 35368894, 2022). "Limited studies have reported the role of PPM1E in thyroid cancer." (PMID 35368894, 2022). "LINC01087 can promote the proliferation and apoptosis of thyroid cancer cells, and its mechanism may be related to the miR-135a-5p/PPM1E axis." (PMID 35368894, 2022). "Has-miR-135a-5p inhibited the malignant evolution and EMT of thyroid cancer by targeting PPM1E." (PMID 35368894, 2022). "Therefore, LINC01087 may regulate the expression of PPM1E through miR-135a-5p, thereby affecting the proliferation and metastasis of thyroid cancer cells." (PMID 35368894, 2022). "The PPM1E overexpression can reverse the inhibitory effect of LINC01087 gene knockdown on the proliferation, migration, and invasion of thyroid cancer cells." (PMID 35368894, 2022). "In addition, LINC01087 silencing suppressed thyroid cancer cell proliferation, invasion, and EMT via the miR‐135a‐5p/PPM1E axis." (PMID 39023191, 2024). "This study investigated the effects of LINC01087 in thyroid cancer cells and whether LINC01087 could affect the proliferation and invasion of thyroid cancer cells by regulating miR-135a-5p and PPM1E." (PMID 35368894, 2022).
Osteoblastoma (1 paper, 2017). A rare benign bone-forming neoplasm usually arising from the spine. "Intriguingly, Ppm1e shRNA knockdown similarly induced AMPKα1 phosphorylation, causing osteoblastoma cell proliferation." (PMID 28460435, 2017). "Here, we demonstrated that miR-135b-5p expression was downregulated in human osteoblastoma tissues, which was associated with Ppm1e upregulation." (PMID 28460435, 2017). "First, we tested expression of miR-135b-5p, the Ppm1e-targeting miRNA, in human osteoblastoma tissues." (PMID 28460435, 2017). "Forced-expression of miR-135b-5p silenced Ppm1e and potently inhibited osteoblastoma cell proliferation in vitro and in vivo." (PMID 28460435, 2017). "We showed that microRNA-135b-5p (“miR-135b-5p”), the anti-Ppm1e microRNA, was significantly downregulated in human osteoblastoma tissues." (PMID 28460435, 2017). "Collectively, miR-135b-5p expression causes Ppm1e silence and AMPK activation in human osteoblastoma cells." (PMID 28460435, 2017). "On the other hand, shRNA-mediated Ppm1e knockdown potently inhibited osteoblastoma cell growth in vivo and in vivo." (PMID 28460435, 2017). "Intriguingly, we here proposed that Ppm1e is the primary target of miR-135b in mediating its inhibition against osteoblastoma cells." (PMID 28460435, 2017). "Together, our results suggest that miR-135b-induced Ppm1e silence induces AMPK activation to inhibit osteoblastoma cell proliferation." (PMID 28460435, 2017). "Above results have shown that forced-expression of miR-135b-5p silenced Ppm1e and inhibited osteoblastoma cell proliferation." (PMID 28460435, 2017). "If Ppm1e is the direct target of miR-135b-5p, knockdown of Ppm1e shall also inhibit osteoblastoma cell proliferation." (PMID 28460435, 2017). "On the other hand, miR-135b-5p's target, Ppm1e mRNA, was upregulated in osteoblastoma tissues." (PMID 28460435, 2017). "Notably, we showed that Ppm1e expression was significantly elevated in osteoblastoma tissues." (PMID 28460435, 2017). "shRNA-mediated knockdown of Ppm1e mimicked miR-135b-5p's actions, and similarly induced AMPK activation and inhibited osteoblastoma cell proliferation." (PMID 28460435, 2017). "In cultured human osteoblastoma cells (MG-63 and U2OS lines), forced-expression of miR-135b depleted Ppm1e, leading to profound AMPK activation (AMPKα1 phosphorylation at Thr-172)." (PMID 28460435, 2017). "We conclude that miR-135b silences Ppm1e to provoke AMPK activation and inhibit osteoblastoma cell proliferation." (PMID 28460435, 2017). "In the current study, we showed that miR-135b-5p expression silences Ppm1e, which activates AMPK to inhibit osteoblastoma cell proliferation." (PMID 28460435, 2017). "Forced-expression of miR-135b-5p in human osteoblastoma cells (MG-63 and U2OS lines) silenced Ppm1e, and induced a profound AMPKα1 phosphorylation (at Thr-172)." (PMID 28460435, 2017).
Tumor (4 papers, 2007 to 2020). "Together, these results indicate that U2OS tumor growth in SCID mice is inhibited after expressing Ppm1e shRNA or miR-135b-5p." (PMID 28460435, 2017). "Further in vivo studies demonstrated that U2OS tumor growth in mice was dramatically inhibited after expressing miR-135b-5p or Ppm1e shRNA." (PMID 28460435, 2017). "Estimated daily tumor growth (in mm3 per day) was also significantly lower in Ppm1e shRNA- or Vec-miR-135b-expressing tumors." (PMID 28460435, 2017). "The expression levels of PPM1E were very low across all 26 tumour samples and, additionally, both PPM1E and TBX4 showed highest expression levels in non-amplified tumour samples." (PMID 17353917, 2007).
cancer (3 papers, 2017 to 2024). A tumor composed of atypical neoplastic, often pleomorphic cells that invade other tissues. "Ppm1E protein expression was also increased in above cancer cells." (PMID 28423719, 2017). "Significantly, Ppm1E upregulation was correlated with AMPK in-activation (or AMPKα1 de-phosphorylation) and mTORC1 activation (or p-S6K1) in cancer tissues." (PMID 28423719, 2017).
PPM1E also shares sentences with these, for which no sentence is quoted: bipolar disorder (1 paper); colon cancer (1); ovarian carcinoma (1); prostate carcinoma (1); testicular germ cell tumor (1).